ALDH1A1 (aldehyde dehydrogenase 1 family member A1)
Diseases named in the same sentence as ALDH1A1 in open-access papers (continued):
Sharing a sentence is not in itself a finding about the gene and the disease.
cancer (1,088 papers, 2005 to 2026). A tumor composed of atypical neoplastic, often pleomorphic cells that invade other tissues. "ALDH1A1, a key aldehyde dehydrogenase isoform, is linked to cancer stem cells (CSCs) and epithelial–mesenchymal transition (EMT) and used as an EMT marker for metastasis-initiating cells (MICs)." (PMID 40227834, 2025). "Although ALDH1A1 has been associated with tumor progression in different cancers, we identified a tumor suppressor role of ALDH1A1 in ITAC." (PMID 41463190, 2025). "Depletion of PIPKIγi5 significantly increased ALDH1A1 expression, supporting that loss of PIPKIγi5 enhances the enrichment of cancer subpopulations with higher sphere formation ability." (PMID 40784457, 2025). "An intracellular enzyme called ALDH1A1 is involved in the oxidation of aldehydes and is a hallmark of CSCs in several different forms of cancer." (PMID 39452555, 2024). "A significant upregulation of ALDH1A1 protein, which is associated with cancer stemness and metastatic potential 46, was also observed in the CML-treated group compared to the control group." (PMID 38250151, 2024). "T cell-mediated cancer cell killing experiments revealed that Aldh1a1 downregulation in CT26 cells rendered them more susceptible to T cell-mediated killing." (PMID 39107297, 2024). "The metastatic potential of OS cells is correlated with aldehyde dehydrogenase 1A1 (ALDH1A1) activity and overexpression is associated with poor cancer prognosis in some cancers and resistance to doxorubicin and cisplatin therapy in vitro." (PMID 38674143, 2024). "This innovative approach resulted in the development of a specific probe tailored for ALDH1A1, a recognized marker linked to resistant cancer cells." (PMID 38495994, 2024). "ALDH1A1 activity is closely linked to functional cancer stem cells via catalyzing the biosynthesis of retinoid acid which triggers the activation of PI3K/AKT, hypoxia, NOTCH, and Wnt/β-catenin pathways." (PMID 38720782, 2024). "The clinical impact of phenotype plasticity of cancer stem-like cells becomes visible when examining ALDH1A1 gene expression in different risk groups of AML, and when comparing primary and recurrent disease." (PMID 39201306, 2024). "Our functional assays using a T cell-mediated cancer cell killing assay demonstrated that ALDH1A1 deficiency in various tumor cells significantly enhances T cell-mediated cytotoxicity by suppressing tumor glycolytic levels." (PMID 39107297, 2024). "Two cancer-risk mutations found in ALDH1A1 (R395H) and ALDH1A2 (R412W) show a similar structural location at the NAD(P)+ binding region." (PMID 37373306, 2023). "We also analyzed the expression of cancer stem cell markers ALDH1A1, CD24, and CD44, which are often associated with EMT induction." (PMID 37834189, 2023). "Elevated levels of ALDH1A1 is considered a marker of cancer stem cells, and is often associated with poor outcomes of various cancers and chemotherapy resistance." (PMID 37429899, 2023). "Several previous studies have reported that many molecules and signal pathways are involved in the mechanism underlying ALDH1A1 regulation in cancers." (PMID 35814382, 2022). "A vast literature demonstrates that aldehyde dehydrogenase-1A1 (ALDH1A1) mediates therapy resistance and is associated with poor prognosis across human cancers." (PMID 35855453, 2022). "We analyzed mRNA expression and activity of a well-characterized cancer stemness marker, aldehyde dehydrogenase1alpha1(ALDH1A1), which was reported to be associated with platinum resistance and poor prognosis." (PMID 35159173, 2022). "ALDH1-A1, an isozyme associated to cancer stem-cells in many solid tumors, is another breast CSC marker, involved in self-renewal, differentiation and self-protection." (PMID 34548908, 2021). "Here, we found that GBP5 knockdown decreased several chemotherapy resistance-associated cancer stemness markers such as ALDH1A1, ALDH1A2, CD44, CD166, and ABCG2." (PMID 34439200, 2021).
cancer (continued). "We also found that the expression of TRIB3 was increased in EC tumorspheres and that the knockdown of TRIB3 caused a reduction in the CSC marker ALDH1A1, as well as cancer stemness genes." (PMID 33334065, 2020). "CSCs exhibit elevated ALDH1A1 catalytic activity, and metabolic inactivation of selected anti-cancer agents by such activity is believed to underlie chemoresistance and consequent cancer recurrence." (PMID 35582039, 2020). "The overexpression of ALDH1A1 is mostly involved in poor cancer prognosis, however, numerous studies suggest that high expression of ALDH1A1 is also associated with a better prognosis of the patients." (PMID 32039729, 2020). "Long noncoding RNAs TP73-AS1 enhances the resistance of GBM cancer stem cells to TMZ by promoting the expression of ALDH1A1, which encodes the aldehyde dehydrogenase 1 family member A1 protein and is enriched in cancer stem cell populations." (PMID 31450721, 2019). "ALDH1A1 expression and activity have been implicated in tumor cell proliferation, cancer stem cell renewal, invasion and drug resistance." (PMID 31208996, 2019). "The purpose of our cancer model is to facilitate the expansion of disease-relevant tumor cells, we tested for expression of ALDH1A1, a described marker of cancer stem cells associated with inferior survival in HNSCCs." (PMID 31181618, 2019). "There is increasing evidence that intracellular marker ALDH1A1 is associated with the CSC phenotype in different types of cancer." (PMID 31601234, 2019). "In cancer stem cells, the overexpression of ALDH1A1 is associated with enhanced invasion, colony formation, and chemoresistance." (PMID 31315286, 2019). "Among the various isoforms, ALDH1A1, 1A2, and 1A3 have been shown to be expressed and active in cancer and have been implicated in the development of chemo-resistance, a key characteristic of CSCs." (PMID 30965686, 2019). "Previous studies reported that CSC biomarkers such as NANOG, OCT4, SOX2, KLF4 and ALDH1A1 were associated with a poor prognosis in several cancers." (PMID 29615105, 2018). "The development of drug resistance in CSCs model is associated with the expression of ALDH1A1 by cancer stem cells." (PMID 30583585, 2018). "ALDH1A1 overexpression, which is observed in various cancer types, has been associated with cancer cell stemness, treatment resistance, and poor patient prognosis." (PMID 29245909, 2017). "Increased expression of ALDH1A1 has been identified in a wide-range of human cancer stem cells and is associated with cancer relapse and poor prognosis, raising the potential of ALDH1A1 as a therapeutic target." (PMID 28129349, 2017). "These experimental findings are supported by clinical data, which demonstrates that ALDH1A1 expression is often associated with worse prognosis in breast and other cancers." (PMID 28937653, 2017). "Mutated KRAS induces GLUT1 and stem cell-like properties in human cancer linked to ALDH1A1 expression." (PMID 27863474, 2016). "Future studies should investigate the key signaling pathways that regulate cancer-associated ALDH1A1 or expression of other ALDH isozymes in various types of cancers." (PMID 26783961, 2016). "Changes in the ALDH1A3 isoform is interesting, as this isoform has been linked to many other cancer types and often follows the same pattern of ALDH1A1." (PMID 28280782, 2015). "Recent studies revealed an association between a higher activity of intracellular ALDH1A1 and cancer cell stemness, particularly in pancreatic cancer." (PMID 26244163, 2015). "It is generally accepted that Aldh1a1 is a pro-tumoral enzyme associated to poor prognosis in several cancer types." (PMID 26242870, 2015). "ALDH1A1 is a known cancer stem cell marker associated with a poor prognosis in several cancer types." (PMID 26317550, 2015). "ALDHA1 encodes aldehyde dehydrogenase 1 family member A1, which serves as a marker of cancer-initiating cells and correlates with tumorigenicity." (PMID 24498386, 2014).
cancer (continued). "In several investigations, it has been shown that the abnormal expression of ALDH1A1 in cancer cells is associated with tumor progression." (PMID 25253129, 2014). "ALDH1A1 has become of increasing interest recently due to its strong association with stem cells and as a prognostic cancer marker." (PMID 25926859, 2014). "Of the 19 ALDH isoforms, ALDH1A1 has most often been linked to the increased ALDH activity of cancer stem cells." (PMID 24053169, 2013). "Of the superfamily, ALDH1A1 has gained most attention because current studies have shown that its expression is associated with human cancer stem cells." (PMID 22852552, 2012). "Our findings reveal that ALDH1A1 overexpression in tumor cells correlates with prolonged patient survival in iCC, contradicting its typical association with higher tumorigenicity 54,55, and cancer stem cells." (PMID 39744576, 2025). "Such complexity can be understood considering the recognized physiological cellular roles of ALDH1 isoenzymes, coupled with evidence from several other cancers where ALDH1A1 upregulation was linked to well‐differentiated tumors and favorable prognostic outcomes." (PMID 38400679, 2024). "Furthermore, EIF4G2 KD resulted in enrichment in cells expressing higher levels of markers such as CD133, CD44 and ALDH1A1 associated with aggressiveness, often referred to as cancer stem cells (CSC)." (PMID 38388710, 2024). "Notably, upon EIF4G2KD, ALDH1A1, a prominent marker whose up-regulation is associated with enhanced tumor aggressiveness and therapy resistance in various cancers, including EC, was increased in expression in the CD133+ cells." (PMID 38388710, 2024). "However, a compelling causal mechanism has emerged linking ALDH1A1 to therapeutic resistance from oxidative stress resistance and promotion of the cancer stem cell phenotype." (PMID 39554793, 2024). "Although disulfiram is a non-specific ALDH inhibitor, our findings provide support to the assumption that ALDH1A1 overexpression is associated with metabolic resistance and may represent an effective target for sensitizing cancer cells to cisplatin." (PMID 37954205, 2023). "Furthermore, cisplatin resistance is associated with cancer stem cells (CSCs), in which ALDH1A1, as a novel CSCs marker, Its enhanced activity has been found identified across a number of cisplatin-resistant NSCLC cell lines and tumor samples." (PMID 35592418, 2022). "Given the causal link between ALDH1A1 expression and chemoresistance in some cancers, the identification of high ALDH1A1-expressing tumour represents a clinical challenge that if solved, could significantly improve patient outcomes." (PMID 35656483, 2022). "Moreover, ALDH1A1 overexpression is associated with chemo-radio resistance in esophageal, breast, and mesothelioma cancers." (PMID 35299840, 2022). "As predicted, TAB182 knockdown remarkably attenuated the transcription of stemness-related genes, e.g., ALDH1A1, BMI1and Oct-4, as well as the genes encoding surface markers of cancer stem cells such as p75NGF, while over-expression of TAB182 showed conversed effect." (PMID 36289198, 2022). "Overexpression of ALDH1A1 in many malignancies and cancer stem cells (CSCs) is strongly associated with poor prognosis, as well as tumor aggressiveness and drug resistance during conventional cancer chemotherapy." (PMID 36484016, 2022). "Overexpression of ALDH1A1 in many malignancies and cancer stem cells (CSCs) is closely associated with poor prognosis and promotes tumor aggressiveness and drug resistance during conventional cancer chemotherapy." (PMID 36484016, 2022). "The relationships between these cell types and CSCs were assessed in tumors; for example, stem-cell markers (Nanog, Lgr5, CD44v6, and ALDH1A1) were highly associated with immune cell counts, which revealed that that cancer stemness and immune state should be considered as a whole." (PMID 34745015, 2021).
cancer (continued). "To study whether the activity of ALDH1A1 contributed to mediate the MCF-7 cancer stem-like features, we used loss-of-function and gain-of-function approaches." (PMID 30541574, 2018). "Additionally, increased expression and activity of ALDH1A1 has been identified in a wide-range of human cancer stem cells and are associated with cancer relapse and poor prognosis." (PMID 28129349, 2017). "Given its ability to reduce primary tumor burden and block BMP9-induced tumor cell proliferation in vitro and in vivo, we assessed the effects of ALK1Fc on the relative expression of ALDH1A1, a marker previously associated with cancer stem cell-like properties and poor patient prognosis." (PMID 29259971, 2017). "ALDH1A1 has been implicated in various pathologies, including cancer." (PMID 28978015, 2017). "The differences could be associated with the maturation and differentiation of ALDH1A1 positive cells in cancers." (PMID 26783961, 2016). "As ALDH1A1 has been linked to the resistance of cancer stem cells to chemotherapy, compounds that alter ALDH activity may present an opportunity to target tumour populations resistant to current chemotherapeutic agents." (PMID 27589691, 2016). "Not taking those clinical predictors into consideration in analysis could result in a false inverse association between ALDH1A1 and cancer prognosis." (PMID 26462023, 2015). "In addition to ALDH1A1, there are several other differential proteins that may be associated with cancer development." (PMID 38138996, 2023). "Besides common nodes such as CYPs, APEX1, MAPT, which reflect the same function for cancer, cardiovascular and neurodegenerative as other flavonoid subclasses flavones contains other nodes such as ALDH1A1 in module 5, which reflect potential associations with cancer invasion." (PMID 30158870, 2018). "Moreover, we show that DKK-1 regulates several cancer-related genes including the cancer stem cell marker aldehyde dehydrogenase 1A1 (ALDH1A1) and Ral-binding protein 1-associated Eps domain-containing 2 (REPS2), which are involved in detoxification of chemotherapeutic agents." (PMID 25788273, 2015). "We next performed Western blot analysis to examine the effects of meranzin hydrate on two cancer stemness markers (ALDH1A1 and NANOG) in GBM cells." (PMID 41473403, 2026). "S100A9 upregulates Aldehyde dehydrogenase 1A1 (ALDH1A1) expression and activates the retinoic acid (RA) signaling pathway in osimertinib-refractory cancer cells." (PMID 39998776, 2025). "Higher expression of ALDH1A1 probably favours the survival of cancer stem cells in type 2 endometrial cancer." (PMID 40433700, 2025). "Using lung tumor and cancer cell lines, Zhang et al26 recently showed that production of erythronate can also occur via aldehyde dehydrogenase 1 family member A1 in an NAD+-dependent manner." (PMID 39983608, 2025). "Aldehyde dehydrogenase 1 family member A1 (ALDH1A1), as a key enzyme for retinoic acid biosynthesis and redox balance, is a biomarker of cancer stem-like cells (CSCs)." (PMID 40093000, 2025). "Aldehyde dehydrogenase 1A1 (ALDH1A1), serving as a marker for cancer stem cells, is implicated in tumor growth and metastasis, contributing to drug resistance and reduced antitumor immunity." (PMID 39897050, 2025). "ALDH1A1 has been identified as an oncogenic factor in many types of cancer and has been shown to amplify drug resistance in tumor cells through nucleotide metabolic pathways." (PMID 40224214, 2025). "Aldehyde Dehydrogenase 1 Family Member A1 (ALDH1A1) is a well-recognized marker for cancer cell subpopulations exhibiting high ability for sphere formation." (PMID 40784457, 2025). "Several stemness markers have been associated with cancer stemness and tumorigenesis in UC, including Oct4, CD133, SOX4, ALDH1A1, and components of the HH signaling pathway." (PMID 40892739, 2025).
cancer (continued). "Regarding cancer stemness, Ad-VP3 significantly impaired sphere-forming capacity and reduced the expression of stemness-associated proteins ALDH1A1, KLF4, and Sox2 in a time-dependent manner at 48 h and 72 h post-infection." (PMID 41472305, 2025). "The cancer stem cell marker aldehyde dehydrogenase 1 (ALDH1A1) is underexpressed in AML cells when compared to healthy cells, both at the RNA level and at the protein level, and at least in the former, both in the bone marrow and in peripheral blood." (PMID 40643557, 2025). "ALDH1A1, a member of the ALDH superfamily, is associated with cancer stem cells and has conflicting reports regarding its prognostic role in iCC." (PMID 39744576, 2025). "In primary NPC samples, the expression of CD44v6 and ALDH1A1 was significantly elevated in cancer cells relative to that in chronic nasopharyngitis tissues." (PMID 40244228, 2025). "This analysis revealed a significant positive correlation of ALDH1A1 with several gene sets related to cancer progression and spread, including genes related to tumor cell motility, metastasis, EMT, ECM and adhesion molecules, angiogenesis, and osteogenesis." (PMID 40122809, 2025). "Many studies have independently reported that ALDH1A-expressing cancers are more tumorigenic and predict worse clinical outcomes, while other studies show that ALDH1A1 and ALDH1A3 promote cardiovascular diseases or obesity." (PMID 41210994, 2025). "Cancer stem-like cells have been reported to have lower ROS, and previous research has established that ALDH1A1 is highly expressed in cancer stem-like cells and plays a critical role in the mitigation of redox stress in these cells." (PMID 40076923, 2025). "Alcohol dehydrogenase-1 family member A1 (ALDH1A1) is a marker of chemoresistance and cancer stem-like properties." (PMID 40227834, 2025). "A study has found that tetrahydroxycurcumin is a potent suppressor of aldehyde dehydrogenase 1 family member A1, a cancer stem cell marker developed by highly aggressive EOC cells with the properties of 3D cells." (PMID 41179371, 2025). "ALDH1A1's behavior is complex, regulated by various epigenetic processes, and it acts as a tumor suppressor in certain cancers." (PMID 40119647, 2025). "Mechanistically, FZD5 modulates the expression of ALDH1A1, a functional marker for cancer stem-like cells, in a β-catenin-dependent manner." (PMID 38539211, 2024). "ALDH1A1, as a key ALDH1 isoenzyme associated with stem cell populations, is a cancer stem cell (CSC) marker and involves in self-renewal and differentiation in many solid tumors." (PMID 38212774, 2024). "ALDH1A1 positively regulates cancer cell survival, extravasation, and metastasis, while ALDH1A3 plays the opposite role." (PMID 38928275, 2024). "Probe 23 represents an innovative approach to detecting ALDH1A1 activity with improved specificity and reduced background noise, positioning it as a promising tool for the identification and study of cancer stem cells." (PMID 38495994, 2024). "Our study is the first to date to explore associations of several reproductive variables with the expression of breast stem cell markers CD44, CD24, and ALDH1A1 in cancer-free women." (PMID 38577336, 2024). "The probes' capacity to undergo changes in excitation wavelength and exhibit an increase in fluorescence intensity upon interaction with ALDH1A1 positions them as valuable tools for probing the role of ALDH1A1 in diverse cancers." (PMID 38495994, 2024). "In vitro and clinical trials for repurposing disulfiram for cancer treatment have been considered based on targeting ALDH1A1." (PMID 38371078, 2024). "ALDH1A1 serves as a stem cell marker in various cancers and participates in the maintenance of cancer stem cells." (PMID 38589907, 2024). "At those stages, the expression of molecules that characterize quiescent cancer “stem-like” cells, such as the enzyme ALDH1A1, is also likely to accompany the expression of immune checkpoint molecules by malignant cells." (PMID 39201306, 2024).